WNT1 (Wnt family member 1)
Diseases named in the same sentence as WNT1 in open-access papers (continued):
Sharing a sentence is not in itself a finding about the gene and the disease.
tumor (continued). "Overall, our current data suggest that the profound reduction in mammary repopulating activity combined with the predominance of progenitors over MaSC-containing compartment in the RARα1/KO, by reducing wnt1 target might contribute to the delay in wnt1-tumor development." (PMID 20923554, 2010). "We examined whether a similar process occurs in Wnt-1 tumor cells." (PMID 18570671, 2008). "Wnt/β-catenin signaling activates CTNNB1 (β-catenin) through WNT1, promoting the expression of collagen (such as COL1A1 and COL28A1), thereby increasing the adhesion and matrix invasion ability of tumor cells." (PMID 40989695, 2025). "Glabridin downregulates Wnt1, β-catenin, and downstream proteins Cyclin D1, MMP-2, and Survivin, inhibiting the tumor cell cycle." (PMID 39723390, 2024). "Orp treatment significantly inhibited the expression of WNT1, FZD2, β-catenin, and c-Myc compared to that in control tumor tissues." (PMID 38356709, 2024). "Some targets, such as DLX4, NDRG3, WNT1, MYC, CREB1, and SIRT6, are involved in tumor or cell proliferation." (PMID 39618816, 2024). "The increased tumor growth resulting from LMP2 and/or TAP2 depletion was also partially reversed by suppressing Wnt1 levels." (PMID 37986152, 2023). "A large number of clinical and basic experiments have shown that the members of Wnt family, including WNT1, WNT2, WNT3A etc., are highly expressed in malignant tumour tissues, which can enhance tumour occurrence, growth and metastasis." (PMID 36646807, 2023). "The Wnt1 and Wnt2 usually involved in Wnt/PCP signalling pathway, which plays key roles in guiding cell polarity and tumour cell invasiveness." (PMID 36766788, 2023). "The authors measured a significant decrease in tumor growth and a reduced expression of SOX4, Wnt1, and β-catenin in tumor tissues." (PMID 35955703, 2022). "In conclusion, our current study demonstrates that TDO2 is a direct target of miR-126-5p which regulated tumor progression via influencing the PI3K/AKT and WNT1 pathway." (PMID 35056756, 2022). "IL-1β activates both RAS and Wnt-1 which mediate the elevation of HIF-1α, thus inducing a HIF-1α/IL-1β autocrine loop in GBM tumor cells." (PMID 35572545, 2022). "Consistent with our observations in HER2/neu and Wnt1 transgenic mouse models, residual BT474-M1 lesions contained scattered GFP+ tumor cells that were quiescent, with only ~ 2% expressing Ki67." (PMID 34088357, 2021). "Further analysis of the correlation between the WNT gene family and clinicopathological parameters of UCEC showed that the WNT1, WNT3, WNT7A, WNT7B, WNT8B, and WNT10A genes were expressed at significantly different levels at different tumor stages." (PMID 34565373, 2021). "Consistent with their expression in both myoepithelial and mesenchymal cells, expression of Pdgrfb and Acta2 were increased in residual tumor cells in both the HER2/neu and Wnt1 models." (PMID 34088357, 2021). "Whereas greater than 90% of HER2/neu-Prim1 and Wnt1-Prim1 primary tumor cells were labeled with BrdU over the 2-week period prior to sacrifice, fewer than 9% of HER2/neu-Prim1 and Wnt1-Prim1 residual tumor cells incorporated BrdU over the same time period." (PMID 34088357, 2021). "To this end, we checked if there was differential expression of Wnt ligands including WNT1, WNT3 and WNT10B among normal liver and HCC tumor tissues." (PMID 35003366, 2021). "Several signaling pathways are involved in miRNA-122-mediated tumor suppression, including cyclin G1, pyruvate kinase isoform M2 (PKM2), Wnt family member 1 (WNT1), and paternally expressed gene 10 (PEG10)." (PMID 33540837, 2021). "Genes downregulated in residual tumor cells were dramatically enriched for cell cycle-related and ribosomal gene sets in both the HER2/neu and Wnt1 models." (PMID 34088357, 2021). "Wnt-1 and Wnt-2 have been found to be over-expressed in NSCLC lines and other primary tumour tissues." (PMID 34572606, 2021).
tumor (continued). "WNT1 overexpression can activate the WNT pathway and lead to the transcription of its downstream genes, c-myc, promoting tumor cell division and migration." (PMID 34067359, 2021). "Consistent with the in vitro experiments, the expression levels of RHBDD1, Wnt1, β-catenin and p-GSK-3β were down-regulated in the tumor xenografts of mice in the miR-924 mimic group compared with miR-NC group." (PMID 33041671, 2020). "From our data, we found that WNT1 acts as a cervical SCC promoting factor regulating E-P cadherin switching through the WNT/β-catenin pathway, thereby promoting tumor cell growth and invasion." (PMID 32301035, 2020). "Wnt1-LateEx mice were initially identified by their longer tumor latency, accounting for ∼40% of the MMTV-Wnt1 tumors profiled in this study." (PMID 31213486, 2019). "Similar to the parental tumor, the FACS profile of Wnt1-LateEx Cd49fpos/Epcamneg-injected cells contained two populations." (PMID 31213486, 2019). "The WNT1 gene belongs to the WNT signaling pathway, which is involved in cell proliferation, development, and tumor progression." (PMID 30935390, 2019). "Some of the genes involved include VEGFA (angiogenesis), WNT1 (proliferation), ERBB3 (proliferation), SMAD4 (tumor suppressor), NDRG2 (radioresistance) and EGFR (invasiveness) all leading to tumor aggressiveness." (PMID 30842790, 2019). "Similar to the parental tumor, the FACS profile of these serially transplanted cells contained two populations, indicating that both Wnt1-LateEx populations were capable of reproducing the other." (PMID 31213486, 2019). "Although Wnt1-LateEx tumor FACS profiles also had two FACS populations, the frequencies were distinct from Wnt1-EarlyEx tumors." (PMID 31213486, 2019). "Wnt1-EarlyEx mice were initially characterized by their early tumor latency, accounting for ∼60% of the MMTV-Wnt1 tumors profiled in this study." (PMID 31213486, 2019). "In stark contrast to the collective outpouring of cells from Wnt1 tumour fragments, the majority of migratory TUBO tumour cells migrated as small clusters (<10 cell) (i-iii) or rarer large clusters (>50 cells) separate from the seeded tumour fragment." (PMID 30139956, 2018). "To ensure that the anti-tumor effects of PRDM14-siRNA treatment were due to PRDM14 inhibition, we generated Prdm14 KO; Wnt-1 transgenic mice." (PMID 28423353, 2017). "Wnt1 knockdown 4T1 cells were injected into the mammary fat pads of female BALB/c mice, and tumor formation was monitored." (PMID 26202299, 2015). "Immunohistochemical analysis showed that tumors from leptin-treated mice exhibited higher number of tumor cells showing increased expression of MTA1, Wnt1, β-catenin and cyclin D1 as compared to tumors from vehicle-treated group." (PMID 26036628, 2015). "Tumors from HNK+leptin treatment group showed very low percentage of tumor cells showing expression of MTA1, Wnt1, β-catenin and cyclin D1 providing physiological relevance to our in vitro findings." (PMID 26036628, 2015). "Cytoplasmic expression of SDC1 is positively correlated with tumor-prone proteins (WT1 and WNT1) and membranous expression of SDC1 is positively correlated with the tumor suppressor (P16)." (PMID 24373193, 2013). "miR-34a was also reported to target Notch signaling pathway to inhibit tumor stem cell invasion by directly binding to NOTCH1, DLL1 and JAG1 as well as Wnt signaling pathway by targeting WNT1 and WNT3 genes and TGF-β signaling pathway via Smad4." (PMID 23823624, 2013). "We confirmed the presence of active virus in Mtv-1/NIV infected tissues and using quantitative reverse transcription PCR (qRT-PCR) found that Mtv-1/NIV induced neoplasms (tumors and hyperplasia) commonly expressed the core CIS genes Wnt1, Wnt10b, Rspo2, Fgf3." (PMID 23866257, 2013).
tumor (continued). "However, our earlier study did not establish whether Pea3 is upregulated prior to the formation of frank tumors, since Northern blotting was insufficiently sensitive to detect Pea3 transcripts in mammary glands prior to tumor development from either wildtype or MMTV/Wnt1 mice." (PMID 20107508, 2010). "Here, we report that Wnt1 tumors are more vascularized than Her2 tumors, and SDF1 is a key factor in facilitating Wnt1 tumor growth and angiogenesis." (PMID 20087418, 2010). "Expression of ΔNPEA3En delayed early-onset tumor formation in MMTV/Wnt1 virgin females (P = 0.03), suggesting a requirement for PEA3 factor function for Wnt1-driven tumor formation." (PMID 20107508, 2010). "Recently, several Wnt proteins, including Wnt-1, have been shown to be over-expressed in HCC tumor compared with the corresponding non-tumor tissue from hepatitis B and C-infected patients." (PMID 19778454, 2009). "There were, however, significant differences in the distribution of tumor histologies with an increase in papillary and cribriform tumors, and a decrease in squamous tumors in the SAFB1+/-/Wnt-1 compared to the SAFB1+/+/Wnt-1 tumors." (PMID 19267898, 2009). "We demonstrated that Wnt-1 is highly expressed in human hepatoma cell lines and a subgroup of human HCC tissues compared to paired adjacent non-tumor tissues." (PMID 19778454, 2009). "To confirm the expression of Wnt-1 protein in HCC, we used the anti-Wnt-1 antibody to detect its expression in seven pairs of HCC tissues and their corresponding adjacent non-tumor tissues." (PMID 19778454, 2009). "Second, we observed subtle differences in the histological distribution pattern of the papillary and cribriform tumor types between SAFB1+/+/Wnt-1 and SAFB1+/-/Wnt-1 tumors." (PMID 19267898, 2009). "The ER+ tumor cells T47D, MCF-7, and ZR75.1 have low basal p-ERK1/2 levels that strongly increased in response to Wnt1 treatment." (PMID 17897439, 2007). "The ERBB2-overexpressing tumor cells BT474 and SkBr3 have high basal p-ERK1/2, and both showed a further increase in ERK1/2 activity in response to Wnt1." (PMID 17897439, 2007). "Id1 and Id3 expression, which reflect an immature stage, is observed in the tumor cells of Wnt-1-driven tumors but not in Neu-induced tumor cells." (PMID 41303422, 2025). "Comparing the expression of Wnt1 gene in normal and tumor samples across 21 different tissues had revealed no statistically significant up or down regulation of this gene." (PMID 36056132, 2022). "This analysis showed that the methylation of the WNT1 promoter (cg27196808) was significantly higher in luminal B primary tumors (stages I–IV) than in nontumor controls, and this observation was consistent across all TNM tumor stages." (PMID 36393855, 2022). "Thus, RSPO3 co‐expression with WNT1 affects tumor morphology, and accordingly, distant lung metastases were found in three of nine RSPO3/WNT1 mice." (PMID 36106661, 2022).
tumor (continued). "A clear involvement of p19ARF, and not p16INK4a, in tumor escape from growth constraints such as chemotherapy, was demonstrated in a Wnt1-dependent mouse breast cancer model." (PMID 33445626, 2021). "In contrast, residual HER2/neu tumor cells did not express CK8, whereas residual Wnt1 tumor cells continued to express CK8 and CK14." (PMID 34088357, 2021). "Similarly, CD206+/TIE2+ macrophages recruited by tumor-derived CCL2 induced upregulated Wnt-1 and downregulated E-cadherin in early HER2+ tumor cells, establishing a pre-metastatic niche promoting early cancer dissemination and intravasation." (PMID 34884995, 2021). "Nevertheless, although MMTV–Wnt1 mice did not develop lung metastasis at 2 months from tumor onset, MMTV–Prune-1/Wnt1 mice showed macro-metastasis in the lungs at 97% penetrance." (PMID 33426510, 2021). "As a pair of negative control genes, we selected the Wnt1, a ligand, and Fzd7, a co-receptor in Wnt signaling, and overexpressed them in tumor cells." (PMID 34373756, 2021). "In vivo experiments have also confirmed that NK4 inhibits tumor formation in nude mice, and it may be related to the regulation of DKK1/Wnt1/β-Catenin related pathways." (PMID 34970492, 2021). "In contrast, anti-Wnt1 suppressed proliferation and apoptosis, but did not affect tumor size and growth in diethylnitrosamine-induced hepatocellular adenomas." (PMID 33585487, 2021). "This analysis revealed that genes associated with human mammary stem cells were expressed at significantly higher levels in dormant residual tumor cells compared to all other tumor cell types in both the HER2/neu and Wnt1 models (p value HER2/neu = 2.34E-27; p value Wnt1 = 1.72E−14)." (PMID 34088357, 2021). "In contrast, residual tumor cells in the Wnt1 model did not exhibit increased expression of mesenchymal markers and instead displayed increased expression of the basal epithelial marker Krt14 (CK14) along with luminal epithelial markers Epcam and Cdh1." (PMID 34088357, 2021). "For example, in a transgenic mouse model of Wnt1-driven mammary tumorigenesis (MMTV-Wnt1), a heterogenous mixture of basal and luminal cancer cells demonstrates interclonal cooperation to support their own tumour growth." (PMID 33824479, 2021). "Deletion of FAK in cKO-Wnt1 mice showed a greater trend of delay in tumor appearance at a median latency of 206 days, but the differences between cKO-Wnt1 and Ctrl-Wnt1 mice was not statistically significant (log-rank test, p = 0.1246)." (PMID 32493400, 2020). "Silencing human and murine Wnt1 rescued DCs from b-catenin activation and restored anti-tumor immunity, suggesting that Wnt1 plays non-redundant roles in adaptive immune resistance of lung tumors." (PMID 30926812, 2019). "All 19 members of the Wnt ligands family (Wnt1-Wnt16) had their expression analyzed in 360 HCC tumor tissues and 50 adjacent non-tumor tissues." (PMID 30814912, 2019). "Moreover, several previous investigations demonstrated that an increased Wnt1 expression was detected in human HCC tissue and human hepatoma cell lines and correlated with increased tumor recurrence after curative tumor resection." (PMID 30814912, 2019). "If the inappropriate expansion of these cell populations was truly a stochastic event, we would not have expected to observe such a stark contrast in tumor latency between the two Wnt1 subtypes." (PMID 31213486, 2019). "Rather than impacting tumor cDC infiltration, Wnt1 acts paracrine on intratumoral cDCs to silence expression of chemokine genes." (PMID 30926812, 2019). "Consistent with the importance of tumor-immune interactions in Wnt1-driven tumorigenesis, Wnt1-LLC cells grew faster in immunocompetent but not in immunodeficient RAG mice." (PMID 30926812, 2019). "This is unlikely to be an artifact of tumor location, as both Wnt1-EarlyEx and Wnt1-LateEx tumors sporadically formed in all murine mammary glands." (PMID 31213486, 2019).
tumor (continued). "Following 72 hours of Wnt1 tumour fragment culture in ET-SIM cultures, IHC revealed low levels of cleaved caspase-3 (CC3) at both the free edge of the tumour as well as the edge in contact with the scaffold indicating that the tumour cells remain viable in ET-SIM cultures." (PMID 30139956, 2018). "Using immunohistochemical analysis of the tumor sections, we determined that the expression of ABCG2 (drug resistance marker), β-catenin and WNT1 (stemness markers) were all significantly decreased in the combined treatment group while pro-apoptotic marker, Bax was increased." (PMID 30005681, 2018). "To further confirm the specificity of Wnt1 in tumor sphere formation, we treated cells with Wnt1 ligand with or without Wnt1 knockdown and then evaluated tumor sphere formation." (PMID 26202299, 2015). "This suggests that targeting FGFR1 alone was not sufficient to eradicate the residual Wnt1/iFGFR1 tumor cells." (PMID 26581390, 2015). "In this study, treatment of mice bearing Wnt1/iR1 tumors with BGJ398, a potent and selective inhibitor of the FGFR family of receptor tyrosine kinases, resulted in an altered collagen-enriched stroma observed both during tumor dormancy and recurrence." (PMID 26581390, 2015). "Conditional deletion of Pygo2 in MMTV-Wnt1 animals similarly delayed the tumor onset, indicating that Pygo2 also enhances Wnt1 driven tumorigenesis, remarkably without affecting the Wnt/ß-catenin signaling output." (PMID 25149534, 2014). "The results indicated that expressions of SOX2 and Oct 4, but not those of Wnt-1, 2 and10a, were upregulated in SP cells isolated from D121 tumour cells when compared with those of non-SP cells." (PMID 21468047, 2011). "Our depletion of Gr1+ cells in Wnt1 tumor-bearing mice gave similar but no additional inhibition on Wnt1 tumor growth when combined with anti-SDF1, suggesting that SDF1 and Gr1+ cells have overlapping mechanisms in facilitating tumor growth." (PMID 20087418, 2010). "This degree of inhibition on Wnt1 tumor growth was comparable, but not additive, to the effect observed with anti-SDF1, indicative of overlapping mechanisms of inhibition." (PMID 20087418, 2010). "Immunohistochemical staining of Wnt1 tumor sections showed that regions lacking MECA32+ cells were more abundant and stained vessels were much slimmer in the anti-SDF1 treated tumors relative to control." (PMID 20087418, 2010). "Whereas non-SP cells formed fewer and slower-growing tumours, SP cells over-expressed many genes associated with cancer stem cell and drug resistance: ABCG2, FGF1, IGF1, MYC, SOX1/2, WNT1, as well as genes involved in angiogenesis, Notch and Hedgehog pathways." (PMID 20424609, 2010). "Previous data has shown that the absence of Lrp5 confers resistance to Wnt1-induced tumor development." (PMID 19672307, 2009). "CRISPR/Cas9 mediated Wnt1 gene KO in the HCT116 cell line reduced Wnt1 protein expression, which in turn promoted the release of inflammatory cytokines such as IL-8, IL-6, and GM-CSF and protected cells from Salmonella invasion and reduced tumor cell migration and invasion ability in vitro." (PMID 37993945, 2023).